COMMD3-BMI1 (COMMD3-BMI1 readthrough)
Synonyms: PCGF4; RNF51
Gene: Protein-coding gene on chromosome 10 (22,316,388 to 22,329,542, forward strand). Ensembl gene ENSG00000269897.
Genetic constraint (gnomAD): Loss-of-function variants: 35 observed, 60.6 expected, observed/expected ratio (o/e) 0.58, 90% interval 0.44 to 0.77. The upper end of that interval is the gene's LOEUF score, 0.77, which puts it in group 3 of 6, group 1 being the genes least tolerant of losing a copy. Missense variants: 459 observed, 580.34 expected, observed/expected ratio (o/e) 0.79, 90% interval 0.73 to 0.85. Synonymous variants: 212 observed, 199.84 expected, observed/expected ratio (o/e) 1.06, 90% interval 0.95 to 1.19.